MIR4696 (microRNA 4696)
Synonyms: hsa-mir-4696
Gene: MicroRNA gene on chromosome 11 (74,720,268 to 74,720,337, reverse strand). Ensembl gene ENSG00000265902.
Homologues: Orthologues: chimpanzee MIR4696 (100% identical).